NLRP3 (NLR family pyrin domain containing 3)
Diseases named in the same sentence as NLRP3 in open-access papers (continued):
Sharing a sentence is not in itself a finding about the gene and the disease.
intracerebral hemorrhage (47 papers, 2015 to 2026). A cerebrovascular disorder characterized by bleeding into one or both cerebral hemispheres including the basal ganglia and the cerebral cortex. "Stimulation of CB1R reduces NOX‐2 levels and NLRP3 activation caused by intracerebral hemorrhage, reducing brain injury." (PMID 40245261, 2025). "A study showed that Nrf2 ameliorated early brain injury associated with intracerebral hemorrhage through inhibition of the NF-κB pathway and NLRP3 inflammasome activation." (PMID 35498131, 2022). "Recent studies have also indicated that Peroxiredoxin II reduces neuroinflammation after intracerebral hemorrhage by alleviating neuronal pyroptosis and suppressing NLRP3 inflammasome activation through counteracting ER stress via the PI3K/AKT pathway." (PMID 40083546, 2025). "Zhongfeng Xingnao Decoction was shown to reduce inflammatory responses and the volume of perihematomal edema by regulating the activation of NLRP3 inflammasome after intracerebral hemorrhage, which is related to the CaMKII/NF-κB p65/NLRP3/GSDMD signaling axis." (PMID 41451367, 2025). "Mechanistically, silencing P2X4 blocks the NLRP3/caspase- 1 pathway, demonstrating a neuroprotective effect in an intracerebral hemorrhage mouse model, while administration of an NLRP3 activator induces neuronal impairment in the same model." (PMID 40329125, 2025). "In the following section, we focus on neuroinflammation mediated by microglia and astrocytes, as well as the potential relationship between the NLRP3 inflammasome expressed in these cells and neuroinflammation after intracerebral hemorrhage." (PMID 40083546, 2025). "Emerging studies identify peroxynitrite, a prototypical reactive nitrogen species, as a potent upstream activator of the NLRP3 inflammasome in intracerebral haemorrhage." (PMID 41408503, 2025). "Consistently, a previous study has highlighted the mitigative effect of BA on the brain injury after intracerebral hemorrhage via the suppressions of the NLRP3 inflammasomes and ROS." (PMID 39662962, 2024). "MCC950 preserves the blood–brain barrier (BBB) and decreases cell death by downregulating NLRP3, caspase-1, and IL-1β production in mice with intracerebral hemorrhage." (PMID 35219323, 2022). "NLRP3 inflammasome can also be activated after hemorrhagic stroke, such as intracerebral hemorrhage (ICH) and subarachnoid hemorrhage (SAH), leading to an inflammatory response cascade that further exacerbates brain injury." (PMID 36160384, 2022). "Accumulating evidence suggest that NLRP3 inflammasome and autophagy played an essential role after intracerebral hemorrhage (ICH)." (PMID 35620574, 2022). "The NLRP3 inflammasome is activated after intracerebral hemorrhage, thus promoting neuroinflammation and aggravating brain edema." (PMID 36558410, 2022). "It was reported that in intracerebral hemorrhage brain injury model, ROS was elevated, and NLRP3 inflammasome pathway was activated." (PMID 35993019, 2022). "Another study reported that andrographolide ameliorates intracerebral hemorrhage by blocking the NF-κB/NLRP3 inflammasome pathway." (PMID 34025417, 2021). "For example, MitoQ inhibits the NLRP3 inflammasome, promoting a shift in microglia toward the M2 phenotype in intracerebral hemorrhage-induced brain damage." (PMID 34356130, 2021). "MicroRNA-223 regulates inflammation and brain injury via feedback to NLRP3 inflammasome after intracerebral hemorrhage." (PMID 33150481, 2020). "It has been proved that, in other disease models such as intracerebral hemorrhage model, ischemia/reperfusion injury model, and hemorrhage transgenic amyotrophic lateral sclerosis model, NLRP3 inflammasome is activated in astrocytes." (PMID 31142341, 2019). "Following intracerebral hemorrhage, the NLRP3 inflammasome plays a role in the infiltration of neutrophils." (PMID 30233311, 2018).
intracerebral hemorrhage (continued). "The NLR family, pyrin domain-containing 3 (NLRP3) inflammasome plays a key role in intracerebral hemorrhage (ICH)-induced inflammatory injury, and the purinergic 2X7 receptor (P2X7R) is upstream of NLRP3 activation." (PMID 26475134, 2015). "Therefore, targeting the NLRP3 inflammasome is of great significance for alleviating neuroinflammation following intracerebral hemorrhage." (PMID 40083546, 2025). "Based on this evidence, we hypothesize that the HMGB1/TLR4 pathway promotes NLRP3 expression through NF-κB activation, exacerbating neuroinflammation following intracerebral hemorrhage." (PMID 40083546, 2025). "Previous studies have shown that inhibiting the NLRP3 inflammasome in rats can have an antineurological effect, and inhibiting the activation of NLRP3 inflammasomes could reduce neuroinflammation during intracerebral hemorrhage." (PMID 38683404, 2024). "In this study, an Nlrp3−/− rat model of intracerebral hemorrhage with ventricular extension and primary choroid plexus epithelial cell culture were used to investigate the potential effects of NLRP3-dependent lipid droplet formation and its role in the pathogenesis of posthemorrhagic hydrocephalus." (PMID 36869068, 2023). "It has been demonstrated that NLRP3 activation and formation of NLRP3 inflammasome in microglia surrounding hematoma after intracerebral hemorrhage promotes caspase-1 activation and leads to increased expression of IL-1β/IL-18, inducing and exacerbating aseptic inflammatory response." (PMID 34526897, 2021). "Similarly, a VDAC dimer has been reported to increase ROS production, as well as nucleotide oligomerization domain (NOD)-like receptor family pyrin domain containing 3 (NLRP3) and IL-1β levels in the mouse brain with intracerebral hemorrhage." (PMID 33803845, 2021). "Neuroinflammation was alleviated by blocking of the TRAF6/NLRP3 interaction during intracerebral hemorrhage that may shed new light on intracerebral hemorrhage treatment in clinic." (PMID 33967693, 2021). "The concept of hemorrhage-induced NLRP3 activation is also demonstrated in brain hemorrhage, where the suppression of NLRP3 by recombinant adenovirus mitigates inflammation and brain injury after intracerebral hemorrhage." (PMID 33374506, 2020). "In addition, previous studies have indicated that BBG inhibited the inflammatory response via the P2X7R/NLRP3 axis following intracerebral hemorrhage." (PMID 28486969, 2017). "It has been reported that early brain impairments and neurological deficits induced by intracerebral hemorrhage could be attenuated by regulating the activation of the NLRP3 inflammasome pathway via the stimulation of Nrf2 activity and the Nrf2-induced antioxidant system." (PMID 33954183, 2021). "Active NLRP3 inflammasome, which cleaves the pro-inflammatory cytokines IL-1β to its active form, has been detected in astrocytes in several animal models of intracerebral hemorrhage, such as ischemia/reperfusion injury and hemorrhage transgenic amyotrophic lateral sclerosis." (PMID 31142341, 2019). "Moreover, it was shown that microRNA-223 could inhibit the activation of the NLRP3 inflammasome through the downregulation of the NLRP3 protein expression, thus alleviating the brain injury after intracerebral hemorrhage." (PMID 30233319, 2018). "During intracerebral hemorrhage, reactive oxygen species, produced by NADPH‐oxidase 2 (NOX‐2), are increased and the NLRP3 inflammasome is activated." (PMID 40245261, 2025). "MCC950, an inhibitor of NLRP3, can block NLRP3 activation, improve the BBB after intracerebral hemorrhage and reduce brain injury." (PMID 37962453, 2023). "The present study aims to investigate the role of DRD1 on neuroinflammation in intracerebral hemorrhage (ICH) mice and the potential mechanism mediated by NLRP3 inhibition." (PMID 29301581, 2018). "However, the effects of H2S on neuroinflammation after intracerebral haemorrhage (ICH), especially on the NLRP3 inflammasome, remain unknown." (PMID 28821266, 2017).
intracerebral hemorrhage (continued). "Furthermore, it is worth noting that IF could inhibit the activation of pro-inflammatory microglia after intracerebral hemorrhage, which is related to NLRP3 inflammasome assembly and caspase-1 activation, highlighting the potential of EODF in restraining the NLRP3 pyroptosis pathway." (PMID 39328272, 2024).
endotoxemia (46 papers, 2010 to 2026). "In summary, the NLRP3 protein was sequentially ubiquitinated by K63- and K48-linked ubiquitination, thus preventing the NLRP3 inflammasome activation and restraining endotoxemia." (PMID 35967871, 2022). "Using the NLRP3-S194A knock-in mice, we demonstrated that NLRP3 S194A mutation significantly protects mice from LPS-induced endotoxemia and monosodium urate (MSU)-induced peritoneal inflammation." (PMID 30349539, 2018). "UK5099 effectively suppresses NLRP3‐mediated IL‐1β production in both mouse and human primary macrophages in vitro, as well as in an LPS‐induced endotoxemia model in mice in vivo." (PMID 38946607, 2024). "NIC-12 selectively reduces circulating IL-1ß levels in the LPS-endotoxemia model in mice and inhibits NLRP3 inflammasome activation in CAPS patient monocytes and mouse macrophages with about tenfold increased potency compared with CRID3." (PMID 38519142, 2024). "UK5099, the gold standard mitochondrial pyruvate carrier (MPC) inhibitor, is found to selectively suppress the activation of the NLRP3 inflammasome in both mouse and human primary macrophages as well as in an endotoxemia mouse model." (PMID 38946607, 2024). "Previous work established that NLRP3 is a critical driver of increased IL-1ß levels in serum of LPS-challenged mice, whereas caspase-11 activation promotes lethality in LPS-induced endotoxemia." (PMID 38519142, 2024). "It has been reported that CBLB combined and ubiquitinates the inflammasome NLRP3, leading to its proteasome degradation and migrating endotoxemia." (PMID 38105184, 2023). "In mice subjected to endotoxemia, mitochondrial damage induces inflammation via activation of NLRP3-dependent inflammasome in macrophages." (PMID 34211859, 2021). "In previous studies, it has been shown that LPS- and ATP-induced HMGB1 release is inhibited in macrophage cultures and endotoxemia models due to genetic deletion of NLRP3 or ASC, which are the main components of the NLRP3 inflammatory model." (PMID 34066647, 2021). "Here, we provide the first evidence indicating that NLRP3 inflammasome-generated IL-1β from microglia is the key cytokine in governing the transition of neuroinflammatory phases elicited by severe endotoxemia." (PMID 32070376, 2020). "Taken together, our results from different doses of LPS, plus data from mutant mice, strongly indicate a critical role of the NLRP3-IL1β-IL-1R1 pathway in mediating the transition from acute to chronic neuroinflammation incited by severe endotoxemia." (PMID 32070376, 2020). "NLRP3 gauges the severity of endotoxemia and determines the amount of mature IL-1β to produce from its precursor protein." (PMID 32070376, 2020). "In vivo, our results show that carnosol has remarkable therapeutic effects in mouse models of NLRP3 inflammasome-mediated diseases, including endotoxemia and nonalcoholic steatohepatitis (NASH)." (PMID 32312957, 2020). "A previous study found that suppressing the NLRP3 inflammasome by blocking PKM2-dependent glycolysis protects mice from endotoxemia and polymicrobial sepsis." (PMID 31337751, 2019). "Accordingly, the deletion of NLRP3 or ASC confers significant protection against lethal endotoxemia." (PMID 30134814, 2018). "qPCR analysis demonstrated that aging significantly increased expression of the inflammasome components pro-caspase-1, ASC, and NLRP3 in the liver during endotoxemia." (PMID 25847140, 2015). "In line with the LPS-induced endotoxemia model, the levels of myocardial NLRP3 and pro-IL-1β were also increased 8 hrs post-FIP induction." (PMID 25216263, 2014). "As opposed to controlled in vitro conditions, in vivo LPS-induced endotoxemia could be accompanied with the presence of several stimuli combining with LPS to activate the canonical NLRP3 inflammasome leading to cell death." (PMID 39399507, 2024).
endotoxemia (continued). "To test this hypothesis, we employed the mouse endotoxemia model by intraperitoneal injection of LPS, which has been well described leading to the NLRP3 inflammasome activation." (PMID 37845329, 2023). "To further investigate whether 1,2-diol could inhibit NLRP3 inflammasome in vivo, then we induced endotoxemia model by i.p. injection of LPS." (PMID 35222388, 2022). "To further demonstrate whether PL could inhibit NLRP3 inflammasome in vivo, we first adopted an LPS-induced endotoxemia murine model and observed that PL markedly alleviated the inflammation, which is in line with a previous study." (PMID 35095532, 2021). "As both MIF and NLRP3 have been implicated in the pathogenesis of septic shock, we next investigated the effects of COR123625 on serum IL-1β and IL-18 in a mouse model of LPS-induced endotoxemia." (PMID 29884801, 2018). "In summary, the Chaihu-Shugan-San decoction modulated intestinal microbe dysbiosis, reduced body fat and intrahepatic fat accumulation and alleviated LPS-induced endotoxemia and inflammatory factor expression, which are all processes related to the NLRP3 inflammasome in NAFLD rats." (PMID 30105078, 2018). "In this study, we explored alterations in NLRP3 inflammasome function elicited by the complement anaphylatoxin C5a in vivo using a LPS-induced endotoxemia model and in vitro by exploring innate inflammatory cell activation of NLRP3 in the absence and presence of C5a." (PMID 27382187, 2016). "Both the accumulation of inflammation cytokines especially IL18 and IL1β, and the activation of NLRP3/ASC/Caspase 1 inflammasome complex in damaged colon indicated that endotoxemia-induced colonic mucosa injury might be related with inflammation-related pyroptosis." (PMID 33679744, 2021). "However, whether elevated brain IL-1β levels incited by endotoxemia are NLRP3-dependent remain unclear." (PMID 32070376, 2020). "For example, a second-generation NLRP3 inhibitor, YQ128, selectively inhibited NLRP3 and attenuated inflammation in a murine model of endotoxemia." (PMID 38881893, 2024). "Finally, while our experiments with bone marrow cells demonstrated that NLRP3 enhancement in inflammatory monocytes was uniquely sensitive to C5a stimulation, additional in vivo work is needed to understand the contribution of these cells to the inflammatory response observed during endotoxemia." (PMID 27382187, 2016). "Cardiometabolic comorbidities promote gut dysbiosis, loss of short-chain fatty acid (SCFA)-producing taxa, and disruption of the intestinal barrier, leading to endotoxemia and upregulation of pro-inflammatory pathways such as TLR4- and NLRP3-mediated signaling." (PMID 41599934, 2026). "As shown, IL-1β levels were largely dependent on NLRP3 activation in the LPS-induced endotoxemia model, as IL-1β was substantially reduced in NLRP3-KO control mice, regardless of pharmacological treatment." (PMID 37698938, 2023). "Moreover, we discovered the rising gene and protein expression of an inflammasome complex containing NLRP3, ASC, and cleaved caspase 1 in endotoxemia colons compared to the control ones, which was also decreased by BRD4 inhibition." (PMID 33679744, 2021). "In this study, JQ1 pretreatment inactivated the NLRP3/ASC/caspase 1 inflammasome assembly, and eliminated the elevation of gasdermins, which indicated BRD4 might promoted pyroptosis to lead endotoxemia colon injury." (PMID 33679744, 2021). "Notably, genetic deletion of NLRP3 or ASC, two essential components of the NLRP3 inflammasome, blocked LPS-, ATP- or MSU-induced HMGB1 release in cultured macrophages or during endotoxemia." (PMID 30134814, 2018). "In addition, a role of ASC and NLRP3 in caspase-1 activation in the monocyte, independently of “classical” inflammasome stimuli, explains the resistance to experimental endotoxemia in ASC−/− and NLRP-3−/− mice." (PMID 20195505, 2010).
endotoxemia (continued). "Furthermore, in the LPS-induced endotoxemia model, which is not solely dependent on NLRP3 to elicit an inflammatory response, we observed that BI6727 treatment also reduced TNF-α levels." (PMID 37698938, 2023). "Bromodomain-containing protein 4 (BRD4) was recently found to play a critical role in endotoxemia colon by regulating NLRP3/caspase-1/GSDMD-mediated pyroptosis, and BRD4 inhibition could prevent endotoxemia-induced colon damage through blocking inflammation-related pyroptosis." (PMID 36505474, 2022). "In experimental models of cardiac infarction (DAMP-mediated) or endotoxemia (PAMP-mediated), activation of the NLRP3 inflammasome in either cardiac fibroblasts or myocytes may contribute to the resultant pathology, cardiac fibroblasts being considered as the more important of the two." (PMID 33101273, 2020). "We conclude that the NLRP3 inflammasome is not activated by hypervolemia thus refuting the thesis that endotoxemia may be a main driver for inflammation in H-HD." (PMID 32138278, 2020).